Y_RNA (Y RNA )
Gene: Miscellaneous RNA gene on chromosome 7 (73,403,788 to 73,403,889, reverse strand). Ensembl gene ENSG00000202035.
Homologues: Orthologues: macaque Y_RNA (85% identical), guinea pig Y_RNA (82% identical), dog Y_RNA (77% identical). Paralogues in human: Y_RNA (95% identical), RNY3 (86% identical), Y_RNA (86% identical), RNY3P1 (85% identical), Y_RNA (85% identical), Y_RNA (84% identical), Y_RNA (83% identical), RNY3P14 (82% identical), Y_RNA (82% identical), RNY3P2 (81% identical), RNY3P5 (81% identical), Y_RNA (81% identical), and 96 more.